MAP4K4 (mitogen-activated protein kinase kinase kinase kinase 4)
Diseases named in the same sentence as MAP4K4 in open-access papers (continued):
Sharing a sentence is not in itself a finding about the gene and the disease.
tumor (continued). "Mechanistically, HMMR promotes tumor metastasis by interacting with MAP4K4, which in turn activates the p-JNK/p-c-JUN/MMP1 signaling pathway." (PMID 39990663, 2025). "Mechanistically, HMMR promotes tumor metastasis by binding to mitogen-activated protein kinase kinase kinase kinase 4 (MAP4K4), which activates the p-JNK/p-c-JUN/MMP1 signaling cascade." (PMID 39990663, 2025). "The pathways in this group reflect the influence of MAP4K4 on the tumor microenvironment, immune interactions, and cellular responses to stress, suggesting multifaceted roles in MSI-GC progression." (PMID 39941781, 2025). "For example, MAP4K4 and MAP4K5 have been implicated in regulating lipogenesis and anabolic processes in tumor cells." (PMID 41034525, 2025). "Overall, we elucidated a novel mechanism by which PEPT1‐mediated transportation of dipeptides activates MAP4K4/G3BP2 signaling to accelerate the metastasis of tumor cells." (PMID 38639383, 2024). "As MAP4K4 inhibitors showed significant cytotoxic effects on SR and MR cells in vitro, we proceeded to evaluate the potential anti-tumor effects of PF06260933 in vivo." (PMID 38548749, 2024). "Next, we detected the protein expression of MAP4K4 on the same set of HCC tissues and found that MAP4K4 expression was considerably higher in HCC tissues than that in matched non‐tumor tissues in the 12 paired samples." (PMID 38639383, 2024). "Nevertheless, further investigations are needed to precisely elucidate how HCC tumor cells sense and utilize dipeptides to regulate MAP4K4." (PMID 38639383, 2024). "To further verify the mechanism on the SOX6‐induced senescence of CC cells, we detected the effects of SOX6 in the MAP4K4/WT1–ATF2–TGFβ2 pathways in above xenograft tumor tissues." (PMID 38383842, 2024). "We compared the MAP4K4 gene expression level between normal and tumour samples from the RNAseq dataset of PAAD." (PMID 36683274, 2023). "The gene expression analysis of the clinical samples revealed that MAP4K4 exhibited significantly high expression (p < 0.001, FC = 7.96) in tumour samples compared with normal samples." (PMID 36683274, 2023). "Upstream control of MAP4K4 in tumor cells is exerted by striatin (STRN) family proteins (members of the STRIPAK family)." (PMID 37223681, 2023). "More specifically, MAP4K4 is significantly up-regulated in peritoneal metastasis compared to primary tumor." (PMID 36922678, 2023). "Further studies should address the role of MAP4K4 inhibition in the anti-tumor effects of immunotherapy." (PMID 37223681, 2023). "Combined, these results suggest that the citron homology domain (CNH, 954-1273) is required for MAP4K4-STRIPAK interaction in MB tumor cells." (PMID 35941177, 2022). "How can the tumor-suppressive activity of MAP4K4 via Hippo pathway activation be reconciled with the tumor-promoting activity of MAP4K4 through increasing actin and cytoskeleton dynamics?" (PMID 36568222, 2022). "It was thus suggested to pharmacologically activate MAP4K4 in combination with chemotherapeutic drugs to boost the cytotoxic response in the tumor cells." (PMID 36568222, 2022). "MAP4K4 is overexpressed in MB patient tumor samples and gene expression profiling of 763 primary MB samples revealed that MAP4K4 expression correlates positively with genes involved in endocytosis control." (PMID 35296518, 2022). "We used membrane-impermeable Sulfo-NHS-SS-biotin labeling of intact sgControl (sgCTL, sgC) and sgMAP4K4 (MAP4K4 knockout, sgM4) MB tumor cells, followed by streptavidin protein capture and high-resolution mass spectrometry analysis." (PMID 35296518, 2022). "Remarkably, however, co-depletion of MAP4K4 and STRN3 caused a near-complete eradication of the tumor cells and completely abrogated cell dissemination in vitro." (PMID 35941177, 2022).
tumor (continued). "Importantly, the approved BCR-ABL and MAP4K4 inhibitory drug bosutinib (Bosulif®) restores endothelial barrier functions and reduces vascular leakage, rendering this compound a candidate drug for tumor patients suffering from tumors associated with aberrant MAP4K4 functions." (PMID 36568222, 2022). "We discuss possible implications of novel interactors in tumor growth and dissemination and evaluate potential therapeutic strategies to selectively repress pro-oncogenic functions of MAP4K4." (PMID 36568222, 2022). "Proteomic analysis also identified proteins involved in exosome assembly and secretion as MAP4K4 interactors, raising the possibility that MAP4K4 promotes secretory vesicular trafficking events affecting tumor cell-host tissue interactions more broadly." (PMID 36568222, 2022). "The STRIPAK complex controls Hippo tumor suppressor signaling towards YAP/TAZ transcriptional activation and proliferation by repressing associated Hippo-activating kinases including MAP4K4." (PMID 35941177, 2022). "The gene expression levels of MAP4K4 in tumor and normal (tumor-adjacent) samples were first assessed." (PMID 36292671, 2022). "MAP4K4 activates the Hippo tumor suppressor pathway and thereby represses YAP/TAZ target gene expression and growth." (PMID 35941177, 2022). "We used proximity-dependent biotin identification (BioID) and kinase activity profiling to functionally explore the MAP4K4 interactome in tumor cells." (PMID 35941177, 2022). "We found that MAP4K4 interacts with the STRIPAK complex in MB tumor cells, and that this interaction orchestrates growth and invasion control downstream of FGFR signaling." (PMID 35941177, 2022). "The combined depletion of MAP4K4 and STRN3 in DAOY cells caused a dramatic reduction of tumor area, both under basal condition and under EGF stimulation." (PMID 35941177, 2022). "To determine the MAP4K4 interactome in MB tumor cells, we generated cell lines stably expressing either the BioID2-MAP4K4 fusion proteins or BioID2 alone." (PMID 35941177, 2022). "We compared MAP4K4 mRNA expression levels between normal and tumoral samples and between primary tumor and metastatic samples and showed that MAP4K4 levels were upregulated in the metastatic PCa sample as compared to primary tumor and normal tissue." (PMID 34112843, 2021). "Among the genes associated with shorter survival in PPS20, TRIO, LDHA, MAP4K4 and ARNTL2 contribute to cellular motility/invasiveness/tumor aggressiveness and thus can also be contributing to shorter event-free survival." (PMID 32310997, 2020). "Future studies will focus on discovering patient-specific predictive biomarkers of MAP4K4 inhibition and synergistic pharmacologic combinations for limiting tumor cell migration." (PMID 31570734, 2019). "We sought to determine the efficacy of MAP4K4 inhibition in slice cultures generated from human tumor surgical resections." (PMID 31570734, 2019). "Five genes, CACNB4 (FCMSS 0.65), MAP3K6 (FCMSS 0.66), CD14 (FCMSS 0.66), CACNA2D4 (FCMSS 0.66), and MAP4K4 (FCMSS 1.52) had slightly stronger FC for MSS-specific tumors than for all tumor combined (FCoverall 0.67, 0.73, 0.68, 0.67, and 1.47, respectively)." (PMID 29636593, 2018). "MAP4K4 expression levels showed a highly positive correlation with tumor size, TNM stage and lymph node metastasis in PDAC patients." (PMID 29970191, 2018). "Consistently, depletion of MAP4K4 in MB tumor cells restricts HGF-driven matrix invasion in vitro and brain tissue infiltration ex vivo." (PMID 29796184, 2018). "Our previous data also demonstrated that the MAP4K4 were significantly up-regulated in the tumor and lymph nodes of CRC patients." (PMID 30429233, 2018). "In the present study, the major finding was that miR-141 enhanced the CRC chemosensitivity of 5-FU in vitro and tumor xenografts in vivo by inhibiting MAP4K4 expression." (PMID 30429233, 2018).
tumor (continued). "Consistent with prior study, we found that protein expressions of MAP4K4 were nearly undetectable in normal lung tissues and tumor‐adjacent normal tissues but were drastically increased in tumor tissues." (PMID 28306189, 2017). "Although its function downstream of HGF has been suggested, our findings are the first to demonstrate the involvement of MAP4K4 downstream of c-Met in tumor cells." (PMID 25625039, 2015). "MAP4K4 is also a pro-migratory protein involved in mammalian development and increases tumor cell motility likely through c-Jun N-terminal kinase (JNK)." (PMID 24708576, 2014). "However, the possible modulation of monocytes and macrophages exerted by MAP4K4 in the tumor microenvironment (TME) needs further research." (PMID 39941781, 2025). "Some studies have indicated that members such as MAP4K4 in head and neck cancer may enhance tumor cell migration and chemoresistance by activating the JNK signaling pathway." (PMID 40486910, 2025). "PEPT1 is upregulated in HCC and mediated the transport of dipeptides to enhance the epithelial and mesenchymal transformation of tumor cells by inducing MAP4K4‐dependent G3BP2 phosphorylation, thereby sustaining the survival of tumor cells and facilitating HCC metastasis." (PMID 38639383, 2024). "Moreover, elevated concentrations of dipeptides in HCC cells can induce the expression of MAP4K4, thereby accelerating tumor cell metastasis." (PMID 38639383, 2024). "MAP4K4 can activate downstream pathways that promote tumor cell proliferation." (PMID 37223681, 2023). "Therefore, inhibiting MAP4K4 and the downstream signalling pathways is the key to inhibiting tumour growth." (PMID 36683274, 2023). "In this line, a remarkable finding is the antiproliferative activity of MAP4K4 through activation of Hippo tumor suppressor signaling, which could lead to increased proliferation due to shutdown of Hippo signaling." (PMID 37223681, 2023). "This obviously incites the challenging questions of whether and how modulation of MAP4K4 could be turned into anticancer therapies, and whether such therapies would need to be specifically tailored to the tissue of origin of the tumor." (PMID 36568222, 2022). "Hence, after the identification of MAP4K4 as a promigratory kinase in tumor cells, the focus of the field shifted to the role of MAP4K4 in the control of cytoskeleton dynamics and cell motility." (PMID 36568222, 2022). "It is known that mitogen-activated protein kinases (MAP4K1 and MAP4K4) and the insulin resistance pathway (PRKCD and PRKAB1) may be associated with tumor progression through modulation of gene expression responsible for cell cycle, proliferation, and growth." (PMID 35453789, 2022). "To develop a better understanding of the diverse functions of MAP4K4 and their potential significance in oncogenesis and tumor progression, we have collected and assessed the current evidence of MAP4K4 implication in molecular mechanisms that control proliferation and promote cell motility." (PMID 36568222, 2022). "However, the more recently revealed role of MAP4K4 as an activator of the Hippo tumor suppressor pathway has complicated the understanding of MAP4K4 as an oncogenic driver kinase." (PMID 36568222, 2022). "Hence, MAP4K4 contribution to overall tumor incidence in embryonal or adult tissue carcinomas can thus not be assessed." (PMID 36568222, 2022). "MAP4K4 was upregulated in tumor samples compared with adjacent samples." (PMID 36292671, 2022). "The potential off-target activities of pharmacological MAP4K inhibition and toxicities observed with first-generation MAP4K4 inhibitors argue for the specific repression of certain but not all effector functions of MAP4K4 to halt its oncogenic or tumor-promoting functions." (PMID 36568222, 2022). "This questions the potential of direct MAP4K4 inhibition as a strategy to repress tumor dissemination, as it may lead to increased proliferation due to the shut-down of Hippo signaling." (PMID 36568222, 2022).
tumor (continued). "Consequently, mice with conditional KO of Map4k4 in endothelial cells displayed impaired angiogenesis, which in the tumor context reduced tumor growth rate and vascular perfusion." (PMID 36568222, 2022). "On the other hand, the restored YAP/TAZ target gene expression after co-depletion of STRN3 and MAP4K4 also indicated that tumor growth suppression we observed by this treatment in the tissue cannot solely be explained by its impact on YAP/TAZ target gene expression." (PMID 35941177, 2022). "We presumed that it may make a positive feedback in tiRNA-Gly/RBM17/MAP4K4 axis and may accelerate the tumor-promoting role of tiRNA-Gly in PTC." (PMID 34225773, 2021). "Partial knockdown of MAP4K4 expression promotes oncogenic transformation and tumor formation." (PMID 31913126, 2020). "RNA expression of MAP4K4 was heterogeneous across samples, and was elevated in the laser-dissected subregions from both the Cellular Tumor (CT, p < 6 × 10−9) and Infiltrating Tumor (IT, p < 0.002) relative to the Leading Edge, which consisted primarily of non-neoplastic cells at the tumor margins." (PMID 31570734, 2019). "Moreover, western blot analysis of the implanted tumor tissues revealed significant downregulation of MAP4K4, p-P38 and p-ERK in the miR-98-5p-mimics group compared with those in the control group." (PMID 29970191, 2018). "To test whether depletion of MAP4K4 prevented this infiltration process, we implanted tumor cell spheroids on the surface of cerebellum slices and monitored the dissemination process after five days of incubation." (PMID 29796184, 2018). "MAP4K4 regulates the expression of kinase, transcription factor, transmembrane receptor that is important for cell–cell communication and matrix metalloproteinases in tumor." (PMID 30429233, 2018). "Strikingly, nearly 100% of the tumor cells were stained positive for MAP4K4." (PMID 28306189, 2017). "Xenograft tumor growth in mice using a hepatocellular cell line is substantially inhibited by RNA interference of MAP4K4, indicating a potential therapeutic target that may be useful for treatment of PCa." (PMID 24708576, 2014). "Knock down of MAP4K4 resulted in inhibition of tumor cell migration and invasion." (PMID 20515450, 2010). "However, emerging evidence suggests that MAP4K4 may also act as a tumor suppressor in PDAC, where its depletion leads to enhanced tumor progression via hyperactivation of the AKT, ERK and mTORC signaling pathways." (PMID 41034525, 2025). "Summary of the main ways in which MAP4K4 could stimulate tumor cell growth." (PMID 37223681, 2023). "Notably, the analysis of the microarray data from the two HCC subject cohorts deposited at GEO database (n=214 for GSE14520 and n=91 for GSE102079) revealed that the MAP4K4 gene expression was significantly higher in HCC tumors compared with adjacent non-tumor liver tissues (P < 0.0001)." (PMID 35679904, 2022). "Hence, MAP4K4 function is necessary for brain tissue infiltration and the efficacy of the process may depend on the level of MAP4K4 in the tumor cells." (PMID 29796184, 2018). "Therefore in addition to examine the potential anti-tumor activity of MAP4K4 inhibitors as a standalone therapy, it is also important to test if MAP4K4 inhibitors can be used in combination to overcome resistance to chemotherapy, radiation therapy, targeted therapy and immunotherapy." (PMID 27800153, 2016). "Finally, we could show that MAP4K4 is highly expressed in KS lesions, suggesting an important role for this kinase in tumour development and invasion." (PMID 24244164, 2013). "MAP4K4 and STRN3 cooperate to promote tissue invasion and regulate tumor growth by modulating Hippo signaling." (PMID 41034525, 2025). "STRN3 facilitates the coupling of MAP4K4 to the phosphatase PP2A, thereby suppressing MAP4K4’s tumor-suppressive activity and enhancing the proinvasive behavior of MB cells." (PMID 41034525, 2025).
tumor (continued). "Mechanistically, activated MAP4K4 phosphorylates G3BP2 at T227, thereby promoting EMT signaling and subsequent tumor cell metastasis." (PMID 38639383, 2024). "In summary, our results reveal a novel regulatory signaling axis, PEPT1/MAP4K4/G3BP2, which is critical for inducing tumor metastasis in HCC, and provide a promising therapeutic target and prognostic indicator for patients with metastatic HCC." (PMID 38639383, 2024). "Their results showed that miR-194, a regulator of the MAP4K4/c-Jun/MDM2 signaling pathway, can act as a tumor suppressor and introduced it as a new target for the prevention and treatment of CRC44." (PMID 36854781, 2023). "The highest upregulation in MAP4K4 expression, using a National Cancer Institute (NCI) tumor panel, was reported in glioblastoma cancer cell lines." (PMID 37190200, 2023). "We specifically addressed how MAP4K4 and STRIPAK complex components integrate FGFR-driven oncogenic signaling towards tumor growth, dissemination, and tissue invasion." (PMID 35941177, 2022). "Mechanistically, MAP4K4 interaction with STRN3 and STRN4 represses canonical MAP4K4 activity towards Hippo tumor suppressor pathway activation by bringing the kinase in proximity of PP2A." (PMID 35941177, 2022). "Our study confirms the canonical function of MAP4K4 and of STRIPAK towards hippo signaling and links it to increased colony formation and clonal growth in two different MB tumor cell models." (PMID 35941177, 2022). "Thus, the MAP4K4-dependent maintenance of surface expression of CD155 on growth factor-activated cells could not only affect the migratory potential of the cells but also locally (in the tumor microenvironment) repress immune system activation." (PMID 35296518, 2022). "TRIO, SLC20A1, MAP4K4 and ERRF1 genes which are upregulated in high PPS20 patients, were also shown to be involved in cellular proliferation and/or tumor growth." (PMID 32310997, 2020). "Recent studies have shown that MAP4K4 phosphorylates LATS1/2, activating the Hippo tumor suppressor pathway, leading to YAP1 inactivation." (PMID 31913126, 2020). "Thus, the identification of endocytic activity as a novel effector function of MAP4K4 for migration and invasion control opens new conceptual avenues for tailored therapeutic interventions to selectively target metastatic tumor progression independent of the underlying oncogenic alteration." (PMID 29796184, 2018). "The quantification of the area covered by the expanding tumor cells using the anti-human nuclei signal revealed a further increase in expansion in HGF-stimulated DAOY cells, which was abrogated in MAP4K4-depleted cells." (PMID 29796184, 2018). "Moreover, the staining of PEPT1, MAP4K4, and G3BP2 in tumor and non‐tumor tissues exhibited the same pattern in the lung metastasis mouse model, which was also in accordance with in vitro functional assays." (PMID 38639383, 2024). "Augmented dipeptides induce the expression of MAP4K4 and promote the phosphorylation of G3BP2 at Thr227, leading to the activation of epithelial‐mesenchymal transition (EMT) signaling, which facilitates the metastasis of tumor cells." (PMID 38639383, 2024). "MAP4K4 is known to regulate MLK3 activity, and MLK3 has a significant role in tumor progression and T-cell response; therefore, it will be essential to establish the in-depth role of MAP4K4 and its downstream signaling in malignant and non-malignant diseases." (PMID 37190200, 2023). "This dichotomous functionality of MAP4K4 in tumor cells provides an explanation why MAP4K4 depletion alone is not sufficient to shrink the tumor volume ex vivo, despite the anti-invasive activity of this treatment." (PMID 35941177, 2022). "However, depletion of STRIP1 increases the MAP4K4 activation signature and the invasive potential of tumor cells, suggesting a negative regulatory role of STRIP1, possibly by making MAP4K4 accessible to PP2A." (PMID 36568222, 2022).